NHERF1 (NHERF family PDZ scaffold protein 1)
Diseases named in the same sentence as NHERF1 in open-access papers (continued):
Sharing a sentence is not in itself a finding about the gene and the disease.
prostate carcinoma (continued). "In this regard, our data show that NHERF-1 overexpression inhibits MINDIN-dependent actions on prostate cancer cell migration without affecting cell adhesion." (PMID 33498862, 2021). "We analyzed the expression of NHERF-1 and MINDIN in human prostate samples and in a premetastatic prostate cancer mouse model, based on the implantation of prostate adenocarcinoma TRAMP-C1 (transgenic adenocarcinoma of the mouse prostate) cells in immunocompetent C57BL/6 mice." (PMID 33498862, 2021). "In contrast, NHERF-1 does not affect MINDIN-dependent effects on other osteomimicry factors or on prostate cancer cell adhesion." (PMID 33498862, 2021). "The mechanisms that trigger NHERF-1 downregulation and mobilization from the plasma membrane have not previously been described in prostate cancer." (PMID 33498862, 2021). "To test whether there is an association between MINDIN and the osteogenic-related factor NHERF-1 in prostate cancer, we first analyzed by immunohistochemistry the expression and subcellular localization of MINDIN and NHERF-1 in human prostate control and tumor samples." (PMID 33498862, 2021).
colon carcinoma (4 papers, 2017 to 2023). "The PDZ-scaffold protein NHERF1 is over-expressed in breast and colon carcinomas, associated significantly with aggressive histological grade and poor prognosis." (PMID 29551770, 2018). "In another study, tumor suppressor- Na+/H+ exchanger regulatory factor 1 (NHERF1/EBP50), an adaptor molecule known to suppress Wnt signaling has been observed to be downregulated in colon cancer cells and is associated with decreased survival and increased intestinal tumor burden." (PMID 34552611, 2021). "The up-regulation of NHERF1 induced by the exposure to hypoxia in colon cancer cells depended on the activation of VEGFR2 signaling." (PMID 27999191, 2017). "We investigated the possible interaction between the hypoxia microenvironment and NHERF1 by subjecting colon cancer cells RKO to hypoxia." (PMID 27999191, 2017). "Furthermore, Wnt signaling dependent upregulation of DNMT1 has been shown to be required to trigger hypermethylation of NHERF1 promoter in colon cancer." (PMID 34552611, 2021). "The inhibitory effect of NHERF1 on cell migration was also observed in colon cancer cells HRT-18." (PMID 27999191, 2017). "In colon cancer cells, NHERF1 expression could be increased by the activation of NF-κB signaling and/or the multiple downstream signaling pathway of HIF-1α/VEGF-A induced in the hypoxia microenvironment." (PMID 27999191, 2017). "NHERF1 in turn inhibited the activation of VEGFR2 signaling pathway which could be due to the interaction between NHERF1 and VEGFR2, resulting in the reduction of the migration and invasion of colon cancer cells." (PMID 27999191, 2017). "NHERF1 in turn inhibited the activation of VEGFR2 signaling which could be regulated by the interaction between NHERF1 and VEGFR2, resulting in the reduction of migration and invasion of colon cancer cells." (PMID 27999191, 2017).
cystic fibrosis (4 papers, 2015 to 2025). Autosomal recessive disorder caused by pathogenic variants in the CFTR gene (cystic fibrosis transmembrane conductance regulator), which encodes a chloride and bicarbonate channel expressed in epithelial cells, and follow the diagnosis criteria. "Furthermore, RhoA, Ezrin, NHERF1, and actin form multiprotein complexes that are involved in reorganizing the actin skeleton network, thereby regulating the integrity and function of airway epithelia in cystic fibrosis." (PMID 39668431, 2025). "NHERF1 is an important regulator of different proteins, trafficking and localized as a cystic fibrosis transmembrane conductance regulator, ezrin and β-catenin." (PMID 31336689, 2019). "This is supported by two observations: first, it has previously been reported that a multiprotein complex (NHERF1-CFTR-ezrin-actin) plays a significant role in maintaining tight junction organization and function in cystic fibrosis epithelial cells." (PMID 26594334, 2015).
ependymoma (4 papers, 2015 to 2021). A WHO grade II, slow growing tumor of children and young adults, usually located intraventricularly. "We have recently reported that NHERF1 is associated with the specialized polarity structures from ependymoma and can be used as a reliable diagnostic marker in this tumor due to its high sensitivity for microlumen detection." (PMID 27229317, 2016). "NHERF1 is expressed in ependymal cells and constitutes a highly sensitive diagnostic marker for ependymoma, where it labels membrane polarity structures." (PMID 27229317, 2016). "In this study, the presence of hydrocephalus and of ependymal apical PM defects in NHERF1-deficient mice translated into the characterization of NHERF1-containing precursor polarized structures in ependymoma." (PMID 25775275, 2015). "In anaplastic tumors with foci of classical ependymoma morphology, an abrupt NHERF1 expression loss was noted in the anaplastic component of the tumor, suggesting loss of differentiation in these advanced tumors." (PMID 25775275, 2015). "Interestingly, NHERF1/EBP50 is a strong diagnostic marker for ependymoma in general, is an organizer of polarity structures such as ependymal cilia, and as further discussed in the ST-YAP1 section, has a domain PDZ-2 that binds to both β-catenin and YAP1." (PMID 34944845, 2021). "The sensitive detection of microlumens by NHERF1 antibody revealed loss of these structures in anaplastic foci present in some WHO grade II ependymomas and a drastic reduction in adult anaplastic ependymoma, most likely due to lack of differentiation of the constituent anaplastic cells." (PMID 25775275, 2015). "Moesin but not the related ERM family member merlin, the product of the neurofibromin 2 (NF2) gene, hereafter called NF2, has been shown to colocalize with NHERF1 in the microlumens of ependymoma." (PMID 29983887, 2018). "NHERF1 immunostaining of chordoid meningioma showed a robust dot-like pattern in the majority of cases, similar to that observed in ependymoma." (PMID 29983887, 2018). "In compact areas, true rosettes were apparent and their lumens were labeled by NHERF1 as in ependymoma." (PMID 27229317, 2016). "NHERF1 labeled the apical PM of true rosettes and canals, indicating that in ependymoma NHERF1 specifically labels polarized structures which include a membrane-bordered lumen." (PMID 25775275, 2015). "The apical PM of normal ependyma and the various ependymoma polarity structures, including microlumens, rosettes, and canals, consistently showed PM localization of moesin, similar to NHERF1." (PMID 25775275, 2015). "To investigate the composition of NHERF1 protein complexes in ependymoma, we screened the intracellular localization of the NHERF1 ligands moesin, NF2, PTEN, PDGFRα, EGFR, YAP1, β-catenin and PHLPP2 that have been functionally involved in primary brain tumors." (PMID 25775275, 2015). "The diffuse NHERF1 microlumen pattern was also present in 35.3% and 44.1% of cases with negative or lower epithelial membrane antigen (EMA) staining, respectively, indicating a higher sensitivity of NHERF1 for microlumen detection in ependymoma." (PMID 25775275, 2015). "Our analysis of WHO grade III anaplastic ependymomas showed a greater degree of NHERF1 expression in pediatric cases in comparison to adult tumors." (PMID 25775275, 2015). "Ring-like structures, deemed to be specific for ependymoma, and likely representing larger microlumens, were also labeled by NHERF1 (arrows)." (PMID 25775275, 2015). "A sparse diffuse NHERF1 expression was also observed in some ependymoma cases, with microlumen density similar to that observed in subependymoma cases." (PMID 25775275, 2015). "The lower grade ependymal tumors, including subependymoma and ependymoma, consistently showed NHERF1 microlumen labeling, usually with diffuse pattern." (PMID 25775275, 2015).
ependymoma (continued). "The presence of areas of classical ependymoma morphology with abundant NHERF1 staining in otherwise anaplastic tumors supports the diagnosis in these advanced tumors." (PMID 25775275, 2015). "Focal NHERF1 labeling was observed in two cases of the tanycytic ependymoma subtype, although several other tanycytic ependymomas showed diffuse NHERF1 pattern, and in one case of the giant cell ependymoma subtype." (PMID 25775275, 2015). "Analysis of a comprehensive panel of 113 tumors showed robust NHERF1 labeling of microlumens in 100% of ependymomas, subependymomas, and pediatric anaplastic ependymomas, and in 67% of adult anaplastic ependymomas." (PMID 25775275, 2015). "All 34 ependymoma cases in our series showed NHERF1 expression in microlumens, either in a diffuse pattern (31 of 34 cases), or more rarely, in a focal distribution (3 of 34 cases)." (PMID 25775275, 2015). "NHERF1 also labeled papillary tumors of the pineal region in a microlumen and focal apical membrane pattern, suggestive of a transitional morphology between CP papilloma and ependymoma." (PMID 27229317, 2016). "Importantly, a microlumen NHERF1 pattern similar to the one in ependymoma was evident in all PTPR cases." (PMID 27229317, 2016). "The pattern of NHERF1 staining in the compact growth areas of aCPP2 differed from the patterns seen in CP papilloma or carcinoma, but resembled to that from ependymoma." (PMID 27229317, 2016). "Anaplastic foci and a subset of adult anaplastic ependymomas showed complete absence of NHERF1-labeled polarity structures, consistent with a loss of differentiation in these aggressive tumors." (PMID 25775275, 2015). "This PDGFRα staining, most likely associated with the Golgi apparatus, was focal in ependymomas and was also present in the NHERF1-negative anaplastic ependymoma and anaplastic astrocytoma cases screened." (PMID 25775275, 2015). "Ependymomas express GFAP, S100 protein, EMA, and NHERF1/EBP50." (PMID 34944845, 2021). "The cut off is not as clear in atypical CP papilloma, but an NHERF1 staining pattern similar to CP carcinoma or ependymoma favors a more aggressive phenotype and tumor recurrences." (PMID 27229317, 2016). "NHERF1 staining was present in 35% of ependymoma cases that lacked reactivity for EMA, the routine immunohistochemical marker used for ependymoma diagnosis." (PMID 25775275, 2015). "Interestingly, NHERF1, a marker of apical PM in normal ependyma, consistently highlighted the microlumens of ependymoma regardless of location, attesting to a common origin for these tumors." (PMID 25775275, 2015). "NF2 IHC in normal ependymal lining and ependymomas showed only faint or no labeling of apical PM, respectively, suggesting that NF2, unlike moesin, is not a major ligand of NHERF1 in these polarized structures." (PMID 25775275, 2015).
invasive breast carcinoma (4 papers, 2012 to 2018). A carcinoma that infiltrates the breast parenchyma. "In the present study, we examined the subcellular expression of NHERF1, BRCA1 and PARP1 proteins in invasive breast carcinomas and investigated, for the first time, the relationship among their expression and with patient outcome." (PMID 29029467, 2017).
liver cancer (4 papers, 2012 to 2021). An epithelial or non-epithelial malignant neoplasm that arises from the liver. "Moreover, NHERF1 was recently implicated in the oxidative stress response regulation in liver cancer cells via the recruitment of the MAPK-activated protein kinase 2 (MK2) that belongs to the stress-induced p38 MAPK pathway." (PMID 29551770, 2018).
ovarian carcinoma (4 papers, 2022). A malignant neoplasm originating from the surface ovarian epithelium. "In vitro, the treatment of ovarian cancer cells with LPA induces a mobilization of NHERF1 from cytosol to plasma membrane and then into migratory pseudopodia." (PMID 35223518, 2022). "The biological relevance of NHERF1 in ovarian cancer (OC) pathology has been investigated in several studies." (PMID 35223518, 2022). "Recent studies show that LPA regulates cytosolic NHERF1 to chemotactic cell migration of ovarian cancer cells." (PMID 36601056, 2022). "This comprehensive review provides an update on the recent study on NHERF1 activity and its pathological role in cervical and ovarian cancer, as well as on its probable involvement in the therapeutic landscape of these cancer types." (PMID 35223518, 2022). "Actually, previous reports have shown that Ezrin and its binding protein NHERF1 were upregulated in response to estrogen in breast and ovarian cancers, implying that there might be a potential link between Ezrin and estrogen or ER." (PMID 36386154, 2022). "In an ovarian cancer cell line, depletion of NHERF1/EBP50 led to reduced levels of phosphorylated ERM (pERM) upon stimulation with lysophosphatidic acid (LPA)." (PMID 35198555, 2022).
ductal carcinoma in situ (3 papers, 2011 to 2020). "Cytoplasmic NHERF1 expression progressively increases in cells from ductal carcinoma in situ (DCIS) to invasive and metastatic tissues, and the upregulation of cytoplasmic NHERF1 protein expression is accompanied by a progressive and significant decrease in membranous NHERF1 expression." (PMID 27097111, 2016).
Hydrocephalus (3 papers, 2015 to 2022). Hydrocephalus is an active distension of the ventricular system of the brain resulting from inadequate passage of CSF from its point of production within the cerebral ventricles to its point of absorption into the systemic circulation. "Because of the high levels of NHERF1 in ependyma, and given that impaired ciliary function is a frequent cause of hydrocephalus, we analyzed ependymal cilia by staining with acetylated α-tubulin antibodies." (PMID 27055101, 2016). "Knockdown of NHERF1/slc9a3r1 in zebrafish embryos also causes severe hydrocephalus of the hindbrain and impaired ciliogenesis in the otic vesicle." (PMID 27055101, 2016). "We report here an extensive characterization of the cause of hydrocephalus in NHERF1 knockout animals." (PMID 27055101, 2016). "A proportion of NHERF1-deficient mice also showed dilatation of the lateral, 3rd and 4th ventricles of the brain that define non-obstructive hydrocephalus." (PMID 25775275, 2015). "Furthermore, we report here that the hydrocephalus caused by ablation of NHERF1 is associated with ciliary dysfunction in the ependymal lining of the cerebral ventricles." (PMID 27055101, 2016). "Thus, and largely based on the great similarity between the NHERF1 and Celsr knockout phenotypes, we propose that the hydrocephalus phenotype of the NHERF1-/- mouse is caused primarily by defective PCP resulting from the mislocalization of Vangl2 in the ependyma." (PMID 27055101, 2016). "About 35% of the NHERF1-/- mice showed clinically relevant hydrocephalus between 28 and 32 days after birth." (PMID 27055101, 2016). "A global NHERF1 knockout mouse was reported in 2002, and hydrocephalus was noted as a secondary phenotypic characteristic." (PMID 27055101, 2016). "Comparison of the NHERF1-/- phenotype with other forms of hydrocephalus strongly suggests that the problem lies in a defective PCP signaling pathway." (PMID 27055101, 2016). "Prompted by the observation that these mice also develop non-obstructive hydrocephalus, we mapped the highest NHERF1 expression in the CNS at the specialized apical PM of ependymal cells." (PMID 25775275, 2015). "NHERF1-deficient mice’s lateral ventricle, third ventricle, and fourth ventricle swelled, indicating the formation of non-obstructive hydrocephalus and it can be either mild or severe." (PMID 35903173, 2022). "NHERF1-deficient mice have intestinal brush border structural defects and we report here that they also have disorganized ependymal cilia with development of non-obstructive hydrocephalus." (PMID 25775275, 2015). "NHERF1 expression was highest at the apical of plasma membrane (PM) of ECs, and was involved in the emergence of non-obstructive hydrocephalus through the disruption of ciliary movement of ECs, according to brain sections." (PMID 35903173, 2022). "Hydrocephalus was noted in NHERF1 knockout mice, but the origin of this phenotype has not been investigated." (PMID 27055101, 2016). "Here we report that mice lacking the Na+/H+ Exchanger Regulatory Factor 1 (NHERF1/Slc9a3r1, also known as EBP50) develop profound communicating hydrocephalus associated with fewer and disorganized ependymal cilia." (PMID 27055101, 2016). "Detailed examination of brain slices from severely hydrocephalic NHERF1-/- animals did not reveal obstructions in the ventricles, arachnoid granulations, or the cerebral aqueduct, suggesting that the syndrome is a form of communicating hydrocephalus." (PMID 27055101, 2016).
Hypercalciuria (3 papers, 2019 to 2020). "In addition to higher urine phosphate excretion, NHERF1 KO mice also demonstrate hypercalciuria and hyperuricosuria." (PMID 32937931, 2020). "Likewise, NHERF1-deficient mice show normal kidney morphology but a marked decrease in the BBM expression of Npt2a, resulting in significant phosphate wasting, hypophosphatemia, hypercalciuria, and stone formation." (PMID 32937931, 2020).
melanoma (3 papers, 2016 to 2023). A malignant, usually aggressive tumor composed of atypical, neoplastic melanocytes. "Moreover, an oncogenic function of NHERF1 in the cytoplasm has been proposed in both colorectal and melanoma cells." (PMID 27229317, 2016). "In the context of melanoma progression, PRL3 dephosphorylates Na+/H+ exchanger regulating factor 1 (NHERF1), an interactor of PTEN, promoting the nuclear to cytoplasmic translocation of both NHERF1 and PTEN." (PMID 37064866, 2023). "PRL-3 can dephosphorylate NHERF1 (Na+/H+ exchanger regulatory factor 1) and lead to an increase of NHERF1 and PTEN (a tumor suppressor with growth and survival regulatory functions) in the cytoplasmic localization, leading to the malignant progression of melanoma." (PMID 35098869, 2022).
prostate adenocarcinoma (3 papers, 2011 to 2025). "Altogether, these data suggest that increased levels of MINDIN alter the functionality of NHERF-1 by decreasing its expression and by triggering NHERF-1 mobilization from the plasma membrane to the cytoplasm in prostate adenocarcinoma cells." (PMID 33498862, 2021).
brain tumors (2 papers, 2015 to 2018). "NHERF1 labeling of microlumens was either absent or rarely seen in other types of brain tumors analyzed, denoting NHERF1 as a reliable diagnostic marker of ependymal tumors." (PMID 25775275, 2015).